IGIP (IgA inducing protein)
Description:
Enhances IgA secretion from B-cells stimulated via CD40.
Synonyms: C5orf53; LOC492311
Tractability: Antibody: UniProt places it where antibodies can reach, with medium confidence; UniProt predicts a signal peptide or a membrane-spanning region; its Gene Ontology location is reachable by antibodies, with medium confidence.
Gene: Protein-coding gene on chromosome 5 (140,125,937 to 140,129,392, forward strand). Ensembl gene ENSG00000182700.
Subcellular location: Secreted
Subcellular location (Human Protein Atlas): Vesicles; Predicted to be secreted
Gene Ontology:
Cellular component: extracellular region
Genetic constraint (gnomAD): Loss-of-function variants: 1 observed, 2.18 expected, observed/expected ratio (o/e) 0.46, 90% interval 0.16 to 1.7. That is too few expected variants to judge how well the gene tolerates losing a copy. Missense variants: 42 observed, 51.49 expected, observed/expected ratio (o/e) 0.82, 90% interval 0.64 to 1.05. Synonymous variants: 13 observed, 17.06 expected, observed/expected ratio (o/e) 0.76, 90% interval 0.5 to 1.21.
Homologues: Orthologues: chimpanzee IGIP (98% identical), rabbit IGIP (98% identical), dog IGIP (94% identical), mouse Igip (94% identical).
Diseases named in the same sentence as IGIP in open-access papers:
IGIP is named in the same sentence as 7 diseases in open-access papers, as found by Europe PMC text mining. Sharing a sentence is not in itself a finding about the gene and the disease. The quoted sentences say what the papers report.
hyperlipidemia (1 paper, 2023). "The glucagon to insulin ratio was a significant predictor even after adjusting for HbA1c, LDL-C, and use of hyperlipidemia medications, and the same was true after additionally adjusting for incretins (iGLP-1, iGIP), hsCRP (cardiovascular risk factor), fibrinogen, and uric acid." (PMID 37762748, 2023).
IGIP also shares sentences with these, for which no sentence is quoted: autoimmune disease (1 paper); cancer (1); dementia (1); diabetes (1); glioma (1); neurodegenerative disease (1).